COMT (catechol-O-methyltransferase)
Diseases named in the same sentence as COMT in open-access papers (continued):
Sharing a sentence is not in itself a finding about the gene and the disease.
prostate carcinoma (continued). "We investigated whether functional polymorphisms of CYP17, CYP19, CYP1B1, COMT and UGT1A1 affected the risk of prostate cancer in two different populations of African ancestry." (PMID 27074016, 2016). "Thus, prostate cancer cell xenograft growth in vivo is repressed due to COMT." (PMID 34587154, 2021). "Accordingly, the COMT enzyme may play a role as a tumor suppressor in breast and prostate cancers." (PMID 34209963, 2021). "We also demonstrate the statistically significant down-regulation of DNA methyltransferases (COMT, MGMT, EHMT2, and SIRT1 deacetylase) in saffron-treated prostate cancer cells." (PMID 38201944, 2023). "Additionally, we found higher miR-195 expression levels could relate to poorer overall survival in prostate cancer patients according to TCGA (p = 0.013) and is consistent with reduced COMT expression levels leading to lower overall survival rate in the same cohort." (PMID 34587154, 2021). "In concordance, miR-195 was observed to be upregulated in prostate cancer compared to both normal according to TCGA, and to BPH in our clinical specimens wherein COMT was downregulated in cancer." (PMID 34587154, 2021). "Real-time PCR validated upregulation of miR-195 in clinical prostate cancer specimens as well as DuPro and DU145 and interestingly, luciferase reporter showed miR-195 capable of binding COMT and overexpressing miR-195 could reduce COMT in cells." (PMID 34587154, 2021).
dependence (10 papers, 2009 to 2022). "Since psychotic disorders are often comorbid with alcohol and other substance dependence, we genotyped the two COMT polymorphisms in alcohol, nicotine and opiate dependence." (PMID 22208661, 2011). "Other genetic variations in COMT, most notably the Val/Met 158 polymorphism, has been associated with sensation seeking among women, novelty seeking and reward dependence in Chinese women and extroversion and novelty seeking." (PMID 19693267, 2009). "The rs165774 polymorphism may affect COMT enzyme activity and therefore dopamine inactivation resulting in vulnerability to substance dependence." (PMID 22208661, 2011). "Association of genetic polymorphism of COMT and DRD4 genes with a risk of specific drug dependence." (PMID 33544778, 2021). "Almost consistently, these studies revealed that polymorphisms in COMT, BDNF, and FKBP5 genes might interact with early life stress and cannabis abuse or dependence, influencing various outcomes of schizophrenia spectrum disorders and BD." (PMID 28822116, 2018). "The COMT enzyme accounts for the degradation of dopamine and plays a key role in prefrontal cortical functioning, so it probably affects the cognitive processes involved in substance dependence." (PMID 21857968, 2011). "In conclusion, our study evidenced, for the first time, a correlation between the severity of substance dependence and s-COMT activity and highlighted the correlation between non-self-control and COMT activity, in individuals with SUD." (PMID 35729517, 2022). "Comparisons of Fagerstrom Test for Nicotine Dependence (FTND), Physiological Cigarette Dependence Scale (PCDS), and Cigarette Withdrawal symptoms (CWS-21) among the smokers with different CYP2A6/COMT polymorphisms were not significantly different." (PMID 28472995, 2017).
nicotine dependence (10 papers, 2007 to 2026). Physical and psychological dependence on nicotine. "In contrast, at our moderately stringent analytical threshold, we identified one CpG site that was differentially methylated in COPD patients compared to controls, this CpG site was in COMT, a gene implicated in nicotine dependence and cigarette smoking." (PMID 34895312, 2021). "Low enzyme activity of the Met allele at codon 108/158 (in the rs4680 polymorphism) of the COMT gene, which encodes a key enzyme involved in the metabolic inactivation of dopamine, has been associated with nicotine dependence." (PMID 28472995, 2017). "SNPs have been reported in other related diseases that involve the COMT gene, such as nicotine dependence, and in cancer patients with pain." (PMID 32533012, 2020). "Currently, no studies aimed at examining the relationship between DRD2, DRD3, COMT, and OPRM1 polymorphisms, the 5-HTTLPR genotype, and smoking habit and nicotine addiction in patients with treatment-resistant mood disorders and schizophrenia-spectrum disorders." (PMID 35455685, 2022). "We hypothesized that the ANKK1-DRD2 rs1800497, DRD3 rs6280, COMT rs4633, and OPRM1 rs1799971 polymorphisms, together with the 5-HTTLPR genotype, could be involved in the smoking habits and nicotine dependence in patients with treatment-resistant psychiatric disorders." (PMID 35455685, 2022).
neuroblastoma (9 papers, 2010 to 2026). Neuroblastoma (NB) is the most common solid, extracranial childhood tumor. "The considerations for catecholamine metabolism in neuroblastoma are also somewhat different than in PPGL where COMT is expressed in larger abundance than MAO, the expression of which is also lower than in adrenal medullary chromaffin cells." (PMID 35957826, 2022). "In this study, we demonstrate that Tolcapone kills neuroblastoma (NB) cells in preclinical models by inhibition of COMT." (PMID 28429453, 2017). "Therefore, most catecholamines produced by neuroblastoma cells are metabolized to 4-hydroxy-3-methoxyphenylglycol (MHPG) by catechol-O-methyltransferase (COMT) and monoamine oxidase (MAO)." (PMID 34200415, 2021). "Thus, the combination of VMAT inhibitor with COMT/MAO inhibitor (MYCN-cluster) or MIBG radiation therapy (ATRX-cluster) might be a potential therapeutic strategy for treating neuroblastoma cases." (PMID 33465163, 2021). "Interestingly, Tolcapone has shown promising anticancer potential with neuroblastoma (NB) cells in preclinical models by inhibiting COMT." (PMID 40725140, 2025). "Neuroblastoma differ from PPGL in their relative expression of the primary catecholamine-metabolizing enzymes, MAO and COMT, with the former deaminating enzyme more highly expressed in neuroblastoma than PPGL." (PMID 35957826, 2022). "Dopamine is completely metabolized to homovanillic acid (HVA) by COMT and MAO within neuroblastoma cells." (PMID 34200415, 2021). "While miR-30a-5p and miR-34a-5p have been shown to decrease COMT expression, another miRNA, miR-148b-3p, is noted for its role in regulating COMT indirectly by targeting the ZNF804A gene, which in turn affects COMT expression in human neuroblastoma cells." (PMID 40779062, 2026). "Because the neuroblastoma line SH-SY5Y is dopaminergic and these cells express dopamine receptors, it is conceivable that the effect of COMT transfection on PS might be mediated by dopamine in these cells." (PMID 20520724, 2010).
obsessive-compulsive disorder (9 papers, 2006 to 2024). A disorder characterized by the presence of persistent and recurrent irrational thoughts (obsessions), resulting in marked anxiety and repetitive excessive behaviors (compulsions) as a way to try to decrease that anxiety. "A baseline alteration in COMT function of this nature could contribute to its numerous sexual dimorphisms, including sex differences in its association with disease states such as obsessive compulsive disorder." (PMID 23613951, 2013). "A novel 65 bp deletion was also found in 3′-UTR of catechol-O-methyltransferase (COMT), a gene that likely contributes to obsessive-compulsive disorder (OCD), potentially explaining the ritualistic behavior of PWS patients." (PMID 37674481, 2023). "Another G > A transition rs165599 at the 3′UTR of COMT, predicted to affect gene expression, showed association with ADHD and obsessive compulsive disorder in Jews from Israel." (PMID 24163823, 2013).
substance abuse (9 papers, 2011 to 2024). The use of a drug for a reason other than which it was intended or in a manner or in quantities other than directed. "In this study, a significant relationship was found between the heterozygous genotype of COMT polymorphism and substance abuse." (PMID 33544778, 2021). "In the case of COMT polymorphism, the methamphetamine abusers containing heterozygous Val/Met variant showed a significant association with substance abuse compared to the control subjects." (PMID 33544778, 2021). "Substance abuse subjects with COMT heterozygous mutant variants (Val/Met) showed a 1.66-fold increased risk of substance abuse compared to the control." (PMID 33544778, 2021). "According to the previous studies of COMT polymorphism and substance abuse in the different ethnic groups, the association of genetic variants of COMT Val158Met polymorphism was found in Turkish cannabis abusers, Taiwanese methamphetamine abusers, and Israeli Heroin abusers." (PMID 33544778, 2021). "Further studies could then determine whether COMT inhibitors might be therapeutically effective in treating psychiatric conditions, such as alcohol and substance abuse, that are linked to perturbations in time perception and decision-making." (PMID 30027496, 2018). "Our findings that COMT is associated with both NS personality traits and with the age of onset of heroin use helps to clarify the complex relationship between genetic and psychological factors in the development of substance abuse." (PMID 21857968, 2011). "Genotype and allele distribution of COMT and DRD4 genes polymorphisms in substance abuser and control." (PMID 33544778, 2021). "Association of genetic polymorphisms of COMT and DRD4 genes with the age of onset of substance abuse." (PMID 33544778, 2021). "In summary, while this study has some restrictions, it is the first research in which the relationship between COMT Val158Met and DRD4 120bp VNTR variant and substance abuse in the Bangladeshi population were analyzed." (PMID 33544778, 2021). "It will be important for follow‐up studies to continue elucidating the pathway from dopamine‐related genes such as COMT, to inhibition‐related cognitive functioning, and finally to disinhibitory psychopathological outcomes, including substance abuse." (PMID 28032000, 2016). "Previous studies reported that gender differences are present in different age groups of substance abusers so we used ANCOVA to adjust for gender (as a covariate) when comparing the mean onset age of heroin use across the different COMT genotypes." (PMID 21857968, 2011). "Therefore, the present study is carried out to investigate the association of genetic polymorphism of COMT and DRD4 as a biomarker for increased risk of substance abuse in Bangladesh." (PMID 33544778, 2021). "In conclusion, the present study has demonstrated a significant association of COMT heterozygous variant polymorphism (Val/Met) as well as both homozygous and heterozygous variants of DRD4 120 bp tandem duplication with risk of substance abuse among the Bangladeshi population." (PMID 33544778, 2021). "Further, all the addicted subjects were categorized into three groups- methamphetamine, heroin, and cannabis abusers to analyze whether these COMT and DRD4 polymorphisms can have any influence on the age of onset of individual substance abusers." (PMID 33544778, 2021). "The present study hypothesized that the carrier of the derived allele of both COMT Val158Met and DRD4 120 tandem duplication polymorphisms in the dopaminergic system are associated with the risk of substance abuse." (PMID 33544778, 2021). "Optimal dopamine levels in the PFC, mostly regulated by COMT enzyme levels, is shown to be crucial for decision making, controlling behavioral problems, antisocial behavior and substance abuse, where an increase in dopamine may lead to higher scores on psychopathy." (PMID 35163702, 2022).
substance abuse (continued). "As both high and low activity of COMT may have an adverse effect on reward processing, the association of COMT polymorphism with substance abuse is not likely a simple theory to describe." (PMID 33544778, 2021). "For lacking non-addicted controls, we were unable to determine whether or not the association between COMT variants and NS personality trait were specific to the substance abuse population or, alternatively, also true in the general population." (PMID 21857968, 2011). "Since ADHD subjects frequently exhibit co-morbid behavioral disorders including CD, ODD, and substance abuse, in the present study we have selected nine polymorphic sites in four catecholaminergic genes, DRD2, DRD4, DDC, and COMT, which modulate function of DA." (PMID 24163823, 2013).
cannabis abuse (8 papers, 2013 to 2021). "When drug free, cannabis dependence weakly predicted schizotypal symptoms and COMT genotype had a marginal impact on working memory, along with ethnicity." (PMID 26882038, 2016). "It is an inhibitor of COMT (catechol-O-methyltransferase) and is under research as a possible drug for cannabis dependence." (PMID 24350211, 2013). "Years of cannabis use, gender, ethnicity (white versus other), cannabis dependence and COMT genotype were not significant predictors of acute psychotomimetic symptoms." (PMID 26882038, 2016). "Years of cannabis use, gender, ethnicity (white versus other), cannabis dependence, THC/cannabidiol ratio and COMT genotype were not significant predictors of acute psychotic symptoms." (PMID 26882038, 2016).
metabolic syndrome (8 papers, 2015 to 2024). A cluster of metabolic risk factors for CARDIOVASCULAR DISEASES and TYPE 2 DIABETES MELLITUS. "Therefore to determine whether COMT deficiency was associated with the metabolic syndrome, first we analyzed liver COMT protein levels in mice fed a high fat diet (HFD) for 2 weeks." (PMID 28801594, 2017). "To further address the role of COMT suppression in the metabolic syndrome, we performed a COMT inhibitor (Ro41-0960) treatment in the HFD mice." (PMID 28801594, 2017). "Genetic variations in COMT with lower enzymatic activity could be a trigger for the onset of metabolic syndromes and liver damage." (PMID 35057469, 2022). "Despite this previously identified association between global DNA methylation and AAP-induced metabolic syndrome, only one study has examined gene-specific methylation at the catechol-O-methyltransferase (COMT) gene and reported a negative finding." (PMID 29850476, 2018). "We also confirmed our analysis directly by utilizing a specific COMT siRNA injection in HFD mice that displayed the characteristics of type 2 diabetes and metabolic syndrome." (PMID 28801594, 2017). "Moreover, we categorized metabolic syndrome-related characteristics in the study population by the TXN and COMT SNP genotype, but found that only age differentially-associated depending on the genotype of each SNP." (PMID 26329592, 2015).
Alcohol Use Disorder (7 papers, 2015 to 2025). "In 2021, a study was done on 329 subjects from Lithuania that assessed the effect of Ankyrin Repeat and Kinase Domain Containing 1 - Dopamine Receptor D2 complex (ANKK1-DRD2) and COMT SNP on the risk of alcohol abuse." (PMID 34725583, 2021).
attention deficit-hyperactivity disorder (7 papers, 2009 to 2025). A disorder characterized by a marked pattern of inattention and/or hyperactivity-impulsivity that is inconsistent with developmental level and clearly interferes with functioning in at least two settings (e.g. at home and at school). "In the context of neurodevelopmental disorders, only one study associated an altered activity of COMT in the cerebellum to the impairment of executive function in attention-deficit/hyperactivity disorder." (PMID 34576238, 2021). "In summary, our study of attention deficit hyperactivity disorder comorbid oppositional defiant disorder and its predominately inattentive type highlights the potential etiologic role of COMT in a Chinese sample." (PMID 19228412, 2009). "COMT and DAT1 genotype did not affect reaction time variability in this sample without subjects with attention deficit hyperactivity disorder." (PMID 22844499, 2012).
COVID-19 (7 papers, 2020 to 2022). A disease caused by infection with severe acute respiratory syndrome coronavirus 2. "On partial correlation analyses, the association between the COMT rs4680 Met allele and the prevalence of COVID-19 remained significant at a trend level after correcting for median age and population size (partial r = 0.348, p = 0.096)." (PMID 32879833, 2020). "Second, we identified differential DNA methylation of a CpG loci within the COMT gene in lung parenchymal fibroblasts associated with COPD, a risk factor in COVID-19." (PMID 34895312, 2021). "The primary aim of this study was to investigate the possible associations between selected SNPs of OPRM1 (rs1799971), COMT (rs4680), BDNF (rs6265), and HTR1B (rs6296) and the presence of de novo long-term post-COVID pain in previously hospitalized COVID-19 survivors." (PMID 35893072, 2022). "This exploratory study showed that four polymorphisms associated with pain experience (SNPs of OPRM1 (rs1799971), COMT (rs4680), BDNF (rs6265), and HTR1B (rs6296)), did not appear to predispose for developing post-COVID pain in previously hospitalized COVID-19 survivors." (PMID 35893072, 2022). "The current study did not reveal significant differences in the presence of OPRM1 (rs1799971), COMT (rs4680), BDNF (rs6265), and HTR1B (rs6296) SNPs between previously hospitalized COVID-19 survivors with and without post-COVID pain." (PMID 35893072, 2022).
hearing loss (7 papers, 2012 to 2025). "COMT Val158Met polymorphism can increase susceptibility to the clinical manifestation of tinnitus in those people with hearing loss." (PMID 40217670, 2025). "Studies indicate that mutations in the COMT genes are linked to sensorineural hearing loss due to the degeneration of hair cells." (PMID 40429930, 2025). "One potential limitation of this study is that self-reported hearing loss was used to estimate the association with a missense variant in COMT." (PMID 36359276, 2022). "A missense variant of rs4680 in COMT was significantly associated with increased hearing loss among young adults in a multi-racial/ethnic U.S. population-based cohort." (PMID 36359276, 2022). "For example, recent studies showed a relationship between rs12201199 in thiopurine S-methyltransferase gene (TPMT) and rs9332377 in the catechol-O-methyltransferase gene (COMPT) with cisplatin-induced hearing loss in children." (PMID 25452763, 2014). "Additionally, individuals with the COMT Met allele have a reduced risk of hearing loss, likely due to the protective effect of dopamine on the auditory system." (PMID 40429930, 2025). "The haplotypes rs4646316 G and rs9332377 A carry a low-activity synonymous COMT variant, rs4818, which has an association with cisplatin-induced hearing loss and confers an 11-to-18-fold reduction in COMT protein levels due to alterations in the mRNA secondary structure." (PMID 36359276, 2022). "With this largest meta-analysis performed to date, we show that the influence of TPMT and COMT on the development of cisplatin-induced hearing loss may be less important than previously suggested." (PMID 25551397, 2014). "With the largest meta-analysis performed to date we show that the influence of TPMT and COMT on the development of cisplatin-induced hearing loss may be less pronounced than previously suggested." (PMID 25551397, 2014). "We found that rs4680 (catechol-O-methyltransferase, COMT, Gene ID: 1312) is associated with an increased prevalence of hearing loss." (PMID 36359276, 2022). "The association between COMT and hearing loss has not been reported previously in nationally representative population-based studies." (PMID 36359276, 2022). "It has been suggested that genetic variants in the genes encoding thiopurine S-methyltransferase (TPMT) and catechol O-methyltransferase (COMT) can predict the development of cisplatin-induced ototoxicity and may explain interindividual variability in sensitivity to cisplatin-induced hearing loss." (PMID 25551397, 2014).